SPI1 (Spi-1 proto-oncogene)
Diseases named in the same sentence as SPI1 in open-access papers (continued):
Sharing a sentence is not in itself a finding about the gene and the disease.
clear cell renal cell carcinoma (3 papers, 2022 to 2025). "The role of SPI1 in the tumor immune microenvironment in clear cell renal cell carcinoma (ccRCC) remains unknown." (PMID 36477668, 2022). "SPI1 expression is strongly correlated with immune cell infiltration in clear cell renal cell cancer (ccRCC) and non-responders to anti-PD-1 therapy in the CheckMate 09, 10 and 25 ccRCC trials were more likely to overexpress SPI1 than responders." (PMID 40428397, 2025).
diabetic cardiomyopathy (3 papers, 2023 to 2024). Diabetic cardiomyopathy is a disorder of the heart muscle in people with diabetes. "Our findings revealed the potential regulatory effect of SPI1 on copper homeostasis and cuproptosis in diabetic cardiomyopathy." (PMID 36675183, 2023). "Further findings suggested that SPI1 regulates copper homeostasis in diabetic cardiomyopathy." (PMID 39145311, 2024).
endometrial cancer (3 papers, 2022 to 2025). Primary or metastatic malignant neoplasm involving the endometrium (mucous membrane that lines the endometrial cavity). "The tumorigenicity of SPI1 has been demonstrated in OC and endometrial cancers." (PMID 37807062, 2023).
esophageal squamous cell carcinoma (3 papers, 2022 to 2025). Esophageal squamous cell carcinoma (ESCC) is a type of esophageal carcinoma (EC) that can affect any part of the esophagus, but is usually located in the upper or middle third. "SPI1 can indirectly inhibit radiotherapy-induced ferroptosisof esophageal squamous cell carcinoma cells (Zhao etal., 2023)." (PMID 41259792, 2025). "Likewise, SPI1 has been identified as one of the prognostic genes for esophageal squamous cell carcinoma correlating with M2 macrophage accumulation and poor patient's prognosis." (PMID 36118415, 2022).
fibrosis (3 papers, 2021 to 2025). the formation of excess fibrous connective tissue in an organ or tissue in a reparative or reactive process. "In the present study, we showed that CCN2, which is reported as a promoter of fibrosis, is translocated into the nucleus in fibroblasts and binds to the regulatory region that is conserved among various species, which is located approximately −14 kb upstream from the initiation codon of Spi1." (PMID 41019779, 2025).
intestinal infection (3 papers, 2008 to 2017). "A relevant defect during intestinal infection is reduced SPI-1 expression, which is a consequence of hilD mRNA instability in Dam− mutants." (PMID 22291968, 2012). "In turn, crosstalk between std and SPI-1 may play a role in intestinal infections by preventing expression of SPI-1 in the caecum, an intestinal compartment in which the std operon is known to be expressed." (PMID 22291968, 2012). "Recently SPI1 and SPI2 have been shown to be involved in both systemic and gastrointestinal tract infection of the chicken by S. Typhimurium." (PMID 18230128, 2008).
lung adenocarcinoma (3 papers, 2022 to 2025). A carcinoma that arises from the lung and is characterized by the presence of malignant glandular epithelial cells. "LINC01094 increased the expression of CCL7 in lung adenocarcinoma by binding to the transcription factor SPI1 of CCL7 and promoting its translocation into the nucleus, thus increasing the degree of infiltration of macrophages in lung adenocarcinoma." (PMID 37637063, 2023). "SPI1 and PSTPIP1 were discovered as novel early prognostic biomarkers relevant to innate immune response in lung adenocarcinoma." (PMID 41144480, 2025).
mastitis (3 papers, 2019 to 2025). Inflammation of breast tissue during lactation or postpartum due to an obstructed duct or infection. "SLC11A1 was closely associated with the expression of genes involved in the regulation of the immune response and inflammation, with S100A12, NOD2, TLR2 and SPI1 being closely associated with mastitis resistance." (PMID 40427248, 2025). "42,198,087 G > A) in the seed region of bta-miR-2899 can influence SPI1 expression by modulating the binding affinities of miRNA and target mRNA and thus cause differences in mastitis resistance." (PMID 31096910, 2019). "We furtherly validated a candidate functional SNP (rs109462250) in the seed region of bta-miR-2899, which is associated with mastitis by affecting the interaction of bta-miR-2899 and SPI1 in Chinese Holsteins." (PMID 31096910, 2019). "We predicted a protein interaction network involving SLC11A1 interacting with 10 proteins, of which SPI1, NOD2, TLR2 and S100A12 have been reported as candidate genes associated with mastitis resistance." (PMID 40427248, 2025). "Finally, we predicted the SLC11A1 protein interaction network and found that SPI1, NOD2, TLR2 and S100A12 interacted with SLC11A1 and were reported as candidate genes associated with mastitis resistance." (PMID 40427248, 2025).
osteoarthritis (3 papers, 2023 to 2025). A noninflammatory degenerative joint disease occurring chiefly in older persons, characterized by degeneration of the articular cartilage, hypertrophy of bone at the margins and changes in the synovial membrane. "Our findings provide the first evidence that conditional deletion of SPI1 can exacerbate osteoarthritis progression in a mechanical overload-induced mouse model." (PMID 40229258, 2025). "suggests that inflammatory macrophages in osteoarthritis are extensively affected by ADGRE5 activation of their own SPI1 to regulate of inflammation, phagocytosis, and cell signaling." (PMID 40181977, 2025). "Targeting the SPI1-mediated activation of the PERK-UPRmt signaling pathway has the potential for combating chondrocyte senescence and treating osteoarthritis." (PMID 40229258, 2025). "Based on the previous study, we then evaluate the expression distribution of the MMP, VEGFA, SPI1, and IRF8 in synovial tissues of patients with osteoarthritis." (PMID 36960385, 2023). "The single-cell RNA sequencing analysis was used to evaluate the expression distribution of the MMP, VEGFA, SPI1, and IRF8 in synovial tissues of patients with osteoarthritis." (PMID 36960385, 2023).
osteoporosis (3 papers, 2014 to 2024). A condition of reduced bone mass, with decreased cortical thickness and a decrease in the number and size of the trabeculae of cancellous bone (but normal chemical composition), resulting in increased fracture incidence. "Through bioinformatics analysis, the transcription factor SPI1 is indicated as a possible diagnostic marker in osteoporosis." (PMID 39075522, 2024). "In the context of osteoporosis, bioinformatics analysis suggests that SPI1 could serve as a potential diagnostic marker." (PMID 39075522, 2024). "Dysregulation of SPI1 is linked to the development of osteoporosis." (PMID 39075522, 2024). "To uncover one mechanism by which SPI1 induces osteogenic differentiation in MC3T3-E1 cells, we considered its target genes that are tightly associated with osteoporosis pathogenesis and osteogenic differentiation." (PMID 39075522, 2024). "Besides, STAT3 and SPI1 may also affect heterotopic ossification and osteoporosis in AS through regulating NKT and TH1 cells differentiation." (PMID 35065610, 2022). "Here, we demonstrate that the SPI1/SMAD5 cascade is capable of inducing osteogenic differentiation of MC3T3-E1 cells, the murine pre-osteoblast cells that have been widely applied for the research of osteogenic differentiation in osteoporosis." (PMID 39075522, 2024). "Thus, upregulation of SPI1 and SMAD5 expression may induce bone formation during osteoporosis." (PMID 39075522, 2024).
periodontitis (3 papers, 2023 to 2025). An acute or chronic inflammatory process that affects the tissues that surround and support the teeth. "They find that IF135, MX1, SPI1 and IF144L associated with it are in the periodontitis core PPI network, and C1QB in the periodontitis core ceRNA network." (PMID 38919957, 2024). "In contrast, 8 MRs (ESR1, CEBPB, FOS, BCL6, E2F1, SPI1, STAT3, and ETS1) were consistently expressed at higher levels (U test statistic between 10 and 16) in the periodontitis condition." (PMID 37834287, 2023).
Waldenström macroglobulinemia (3 papers, 2021 to 2024). "The comprehensive understanding of SPI1–DNA interactions, especially in the context of pathogenic mutations, forms a basis for further research into the molecular mechanisms driving transcriptional dysregulation in diseases like Waldenström macroglobulinemia." (PMID 38791216, 2024). "Alterations in SPI1 lead to oncogenic subversion by cellular proliferation and differentiation arrest in Waldenström macroglobulinemia." (PMID 34926275, 2021).
ankylosing spondylitis (2 papers, 2022 to 2024). An autoimmune chronic inflammatory disorder characterized by inflammation in the vertebral joints of the spine and sacroiliac joints. "Recent work has revealed the important activity of SPI1 in facilitating osteogenic differentiation of bone marrow mesenchymal stem cells in acute suppurative osteomyelitis and fibroblasts in ankylosing spondylitis." (PMID 39075522, 2024). "Recent studies have demonstrated that SPI1 is capable of controlling osteogenic differentiation of bone marrow mesenchymal stem cells in acute suppurative osteomyelitis and ankylosing spondylitis fibroblasts." (PMID 39075522, 2024). "It has been demonstrated that the transcription factor SPI1 has key functions during osteogenic differentiation of bone marrow mesenchymal stem cells and ankylosing spondylitis fibroblasts." (PMID 39075522, 2024).
brain inflammation (2 papers, 2021 to 2023). "SPI1/PU.1 is critical for the maturation and regulation of the immune system and brain inflammation and is a potential activator of toll-like receptor (TLR) signaling, complement activation, and cytokine signaling." (PMID 37232723, 2023). "We found strong correlation with a variety of pro‐inflammatory mediators, making SPI1/PU.1 a candidate driver of brain inflammation." (PMID 33786950, 2021).
Co-infection (2 papers, 2009 to 2025). "The co-infection model we used provides a sensitive assay that confirms the role of SPI1 and clarifies the role of SPI2 in the colonization of the chicken by Typhimurium." (PMID 19126220, 2009). "To further test this hypothesis, we performed two co-infection experiments in which the effect of the Δspi2 mutation was analyzed in the absence of SPI1." (PMID 19126220, 2009). "Co-infection of Salmonella with a Salmonella “probiotic” strain that is neither virulent nor capable of consuming F-Asn (a SPI1 SPI2 fraR-BDAE ansB mutant) led to a dramatic 10,000-fold reduction in CFU and a 1000-fold reduction in lipocalin-2, a proxy marker of inflammation." (PMID 41474808, 2025).
dilated cardiomyopathy (2 papers, 2019 to 2022). Cardiomyopathy which is characterized by dilation and contractile dysfunction of the left and right ventricles. "Similarly, Qiao found that SPI1 plays a key role in the occurrence and development of ischemic cardiomyopathy and dilated cardiomyopathy by regulating apoptosis- and inflammation-related genes." (PMID 35864510, 2022). "Similarly, Qiao’s study also reported that SPI1, ZBTB7A, and IRF8 play crucial roles in the development of dilated cardiomyopathy and ischemic cardiomyopathy by regulating inflammation- and apoptosis-related genes." (PMID 31850068, 2019).
enterocolitis (2 papers, 2019 to 2024). An inflammatory process affecting the small intestine and colon. "Moreover, enterocolitis and human intestinal epithelial cell invasion may be influenced by the regulation of virulence factors including HilA, invA, and SPI-1 effectors such as SipA and SopABD." (PMID 38222969, 2024). "However, a detailed analysis of the exact role of the individual SPI-1 and SPI-2 effectors during human enterocolitis remains to be elucidated." (PMID 31214517, 2019).
enteropathy (2 papers, 2023 to 2025). "Using our SPI-2 multimutant strains, we observed relatively little difference in the induction of enteropathy in the caecal tissue, which is a hallmark of oral infection in mice and driven largely by the SPI-1 T3SS10,37,38." (PMID 41198616, 2025). "This mutant strain is still able to trigger SPI-1 -dependent invasion and gut inflammation and the enteropathy is about as pronounced as for wt S.Tm infections, at least during the first 2 days of infection." (PMID 37384776, 2023). "It employs wt S.Tm (i.e., intact SPI-1 and SPI-2) that elicits enteropathy and is further characterized by the successive development of a typhoid-like disease, which can overwhelm Nramp-1-negative mouse strains at later time points (beyond days 5–6 p.i.)." (PMID 37384776, 2023).
experimental autoimmune encephalomyelitis (2 papers, 2022 to 2023). An autoimmune demyelinating disease of the central nervous system that is produced experimentally in animals by the injection of homogenized brain or spinal cord in Freund's adjuvant. "Chr 3: MIR124-2 host gene is the most abundant brain-specific miR, promotes microglial quiescence, inhibits microglial and astrocyte activation, and suppresses experimental autoimmune encephalomyelitis by deactivating macrophages via the CEBPA/C/EBP-a-SPI1/PU.1 pathway." (PMID 37987368, 2023).
familial hypercholesterolemia (2 papers, 2018 to 2025). An inheritable form of hyperlipidemia, in which there are excess lipids in the blood. "SPI1 is vital in the familial hypercholesterolemia relatedregulatory network." (PMID 41259792, 2025).
Hypertension (2 papers, 2022 to 2025). The presence of chronic increased pressure in the systemic arterial system. "Hypertension was associated with two other AD risk alleles, located at the SPI1 locus (rs10437655_A) and MME locus (rs61762319_A), respectively." (PMID 41466307, 2025).
immuno-deficiencies (2 papers, 2016 to 2025). "This case expands the known mutational spectrum of SPI1-related immunodeficiency and underscores the critical challenges in its management." (PMID 41394874, 2025). "To date, human cases of SPI1-related immunodeficiency have been reported in only a limited number of publications, highlighting the scarcity of clinical data and the importance of further characterization." (PMID 41394874, 2025).
kidney cancer (2 papers, 2022 to 2025). Primary or metastatic malignant neoplasm involving the kidney. "SPI1 synergistically promotes the inhibition of lipid peroxidation in kidney cancer cells with the epigenetic molecule EZH2, and its target is ACSL4, a key molecule for ferroptosis." (PMID 41372608, 2025). "While limited research has delved into the correlation between ccRCC and ferroptosis, the role of SPI1 remains ambiguous in the context of kidney cancer and ferroptosis." (PMID 41372608, 2025). "Literature review highlighted SPI1 as a potential key player in kidney cancer development." (PMID 41372608, 2025). "We aimed to explore the relationship between SPI1 and ACSL4 in kidney cancer tissue samples." (PMID 41372608, 2025).
lung fibrosis (2 papers, 2018 to 2025). "In vivo, we conducted conditional knockout mice of SPI1 gene (coding PU.1) and performed bleomycin‐induced lung fibrosis model." (PMID 39888275, 2025).
neuroblastoma (2 papers, 2015 to 2021). Neuroblastoma (NB) is the most common solid, extracranial childhood tumor. "Surprisingly, SPI1 expression could even be induced in the neuroblastoma cell line SH‐SY5Y upon OS in a concentration‐dependent manner." (PMID 33786950, 2021). "Remarkably, we found OS to strongly induce SPI1 expression in a time‐ and concentration‐dependent manner in astrocytes and the SH‐SY5Y neuroblastoma cell line." (PMID 33786950, 2021).
prion disease (2 papers, 2014 to 2020). A transmissible disease that is caused by a protein that is able to induce abnormal folding of normal cellular proteins, leading to characteristic spongiform brain changes, which are associated with neuronal loss without an inflammatory response. "Csf1r is activated together with Cebpa and Spi1 in prion diseases, consistent with a Motif 10 regulatory relationship including Cebpa-Spi1 and Csfr1 in the TRCs." (PMID 31959236, 2020).
tauopathy (2 papers, 2019 to 2022). Neurodegenerative disorders involving deposition of abnormal tau protein isoforms (tau proteins) in neurons and glial cells in the brain. "Further work is necessary to define the role of SPI1/PU.1 in tauopathy." (PMID 35078351, 2022).
uveitis (2 papers, 2020 to 2024). An inflammatory process affecting a part of or the entire uvea. "To date, the majority of research concerning SPI1 in the retina has predominantly centered on ocular inflammation, including conditions such as uveitis, optic nerve injury, and photoreceptor malnutrition." (PMID 38979414, 2024).
alcoholism (1 paper, 2022). "SPI1 is involved in the genetic overlap between alcoholism and neurodegenerative diseases." (PMID 36118709, 2022).
chronic asthma (1 paper, 2023). An asthma that is characterized by the development of persistent airway inflammation and recurrent attacks of breathlessness and wheezing, which vary in severity and frequency. "We define SPI1 as an important disease-associated transcription factor in both tissues and that its pharmacological inhibition may be a novel treatment strategy for the most intractable features of chronic asthma." (PMID 36698141, 2023).
diabetic nephropathy (1 paper, 2023). "The relationship between SPI1, MBD1, and diabetic nephropathy needs further experimental verification." (PMID 37113991, 2023).
diffuse large B-cell lymphoma (1 paper, 2025). "In diffuse large B-cell lymphoma, this includes inhibition of SPIB and SPI1 function, leading to transcriptional repression of oncogenic programs and induction of apoptosis." (PMID 41509392, 2025).
heart failure (1 paper, 2022). Inability of the heart to pump blood at an adequate rate to meet tissue metabolic requirements. "In addition, SPI1 has been predicted to regulate the expression of key genes that lead to heart failure following AMI." (PMID 35864510, 2022).
keratitis (1 paper, 2023). A corneal disease that is characterized by inflammation of the cornea. "Simultaneously, differential gene expression (DGE) and pathway enrichment analysis-specified host transcription factor (SPI1) influences keratitis pathogenesis." (PMID 37836798, 2023).
lentivirus infection (1 paper, 2021). Virus diseases caused by the Lentivirus genus. "The effect of Spi1 shRNA knock down (KD) and Spi1 pSIEW over expression (OE) was assessed in flow cytometric sorted microglia after 11 days of lentivirus infection." (PMID 34294785, 2021).
lymphoid leukemia (1 paper, 2016). A malignant lymphocytic neoplasm of B-cell or T-cell lineage involving primarily the bone marrow and the peripheral blood. "Future experiments are required to determine the contribution of perturbations in Hoxc13 and Spi1 expression to dysregulation of Zfp521, and the potential for alternations in the expression of these transcription factors to promote lymphoid leukemia." (PMID 27506447, 2016).
male infertility (1 paper, 2024). The inability of the male to effect fertilization of an ovum after a specified period of unprotected intercourse. "Therefore, we hypothesize that the significant downregulation of DEGs (CFAP70, TTC29, CCDC40, DNAAF4, SYCE3, STK36, SPI1 and EMX2) in hybrid yellow catfish is the primary cause of male infertility or reduced fertility." (PMID 38891632, 2024).
pulpitis (1 paper, 2020). Inflammation of the dental pulp. "However, associations of LCP2 and SPI1 with pulpitis have not been reported previously." (PMID 33046027, 2020).